CP (ceruloplasmin)
Diseases named in the same sentence as CP in open-access papers (continued):
Sharing a sentence is not in itself a finding about the gene and the disease.
type 1 diabetes (4 papers, 2019 to 2025). "Indeed, evidence of ER stress, using this PL:CP ratio, can be found in children at risk of type 1 diabetes and, in them, predicts the disease, especially in children under the age of 10 years." (PMID 31558146, 2019). "The CP is currently in clinical trials for islet transplantation in type-1 diabetes, demonstrating its capacity to support long-term graft viability." (PMID 41040861, 2025). "Hepatocyte growth factor activator, complement factor H, ceruloplasmin, and age predicted progression time to type 1 diabetes significantly better than age alone." (PMID 33668851, 2021). "Many years ago, we and others found the same altered PL:CP ratio: before type 1 diabetes, but also in identical co-twins of children with type 1 diabetes and in non-HLA identical siblings, who were themselves estimated to be at low disease risk." (PMID 31558146, 2019).
abscess (3 papers, 2012 to 2022). An inflammatory process characterized by the accumulation of pus within a newly formed tissue cavity which is the result of a bacterial, fungal, or parasitic infection or the presence of a foreign body. "With abscesses in the blood of cats, an increase in CT, CP, and GLR is observed against a background of a decrease in glutathione peroxidase." (PMID 34395590, 2021). "The increase in CP values has also been explained on the basis of adherent neuroinflammatory molecules that probably imitate the presence of haphazardly arranged vectors and give the more planer model of diffusion tensor in the abscess cavity." (PMID 36553048, 2022). "The CP8-IsdB antiserum significantly reduced the CFU/abscess formed by CP8 strain PS80 (P = 0.04), as well as those formed by S. aureus strains Newman (CP5) or LAC (CP−) (P = 0.0148 and P = 0.0019, respectively)." (PMID 23077517, 2012).
adrenocortical carcinoma (3 papers, 2022 to 2024). "A recent study showed that reduced expression of FPN1 and CP in adrenocortical carcinoma was associated with poor prognosis, thus supporting these proteins as a potential biomarkers of cancer signature and treatment responses." (PMID 35918659, 2022).
asthma (3 papers, 2019 to 2022). "Our redox proteomic study also confirmed a higher oxidation of ceruloplasmin after 1 month of both treatments, probably counteracting the asthma-induced oxidative stress." (PMID 35453511, 2022). "CP levels are elevated during oxidative stress including the course of asthma." (PMID 34836256, 2021). "In our previous proteomic work on comparison of SEA serum protein profiles at T0 and T1 of both monoclonal therapies, we found upregulation of some protein species of ceruloplasmin (CERU) after 1 month of benralizumab treatment, assuming a lowering of asthma-induced oxidative stress." (PMID 35453511, 2022).
autism spectrum disorder (3 papers, 2021 to 2023). A spectrum of developmental disorders that includes autism, and Asperger syndrome. "Ceruloplasmin, an intrinsic antioxidant protein, maintains copper homeostasis, which might also influence autism spectrum disorder (ASD)." (PMID 37636453, 2023).
breast tumor (3 papers, 2018 to 2022). "In vivo studies on murine breast tumor (4T1 cells)-bearing BALB/c mice demonstrated good dose dependent anti-tumor efficacy of CP-liposomes." (PMID 35893789, 2022). "Furthermore, previous studies showed that the peptide B2RA B-9870 (CU201) can inhibit growth of breast tumor cells, within the same concentration range of the CP-B2RAs used herein." (PMID 29515778, 2018). "In the present work, we proposed to develop CP nanoparticles decorated with specific and novel aptamers able to bind to TNBC cells in order to improve the efficacy of PDT, which is in constant examination preclinically and clinically to treat primary breast tumors." (PMID 35336001, 2022).
cholangiocarcinoma (3 papers, 2015 to 2022). A carcinoma that arises from the intrahepatic biliary tree (intrahepatic cholangiocarcinoma) or from the junction, or adjacent to the junction, of the right and left hepatic ducts (hilar cholangiocarcinoma). "A previous study in the cholangiocarcinoma cell line also pointed to CP’s efficacy to decrease the expression of cyclin A and Cdc25; which are responsible for G2 to mitosis (M) phase transition, resulting in G2/M cell cycle arrest." (PMID 34299510, 2021). "Fourteen proteins (6%) were identified as more abundant in cholangiocarcinoma, including such proteins as intercellular adhesion molecule 1, ceruloplasmin, haptoglobulin, complement c3, and -c4b." (PMID 25304323, 2015).
chronic heart failure (3 papers, 2012 to 2025). "Apolipoprotein E, tropomyosins, alpha-2 macroglobulin, complement 3, creatin kinase B and ceruloplasmin have been also described as biomarkers for chronic heart failure." (PMID 22384053, 2012).
coagulopathy (3 papers, 2022 to 2023). "The Chinese patient also had hypertransaminasemia, hypercholesterolemia, and coagulopathy but with a low level of serum ceruloplasmin." (PMID 38075676, 2023). "However, the hyperbilirubinemia, hypertransaminasemia, coagulopathy, and decreased serum ceruloplasmin persisted, and massive ascites emerged during the approximate 9-month follow-up." (PMID 38075676, 2023). "However, the hypertransaminasemia, hypercholesterolemia, elevated alkaline phosphatase, decreased serum ceruloplasmin and serum copper level, and coagulopathy persisted during the approximate 4-year follow-up." (PMID 35401690, 2022).
coccidiosis (3 papers, 2021 to 2023). A parasitic infection caused by Coccidia. "There is some old evidence suggesting that high levels of CP increase the severity of coccidiosis in chickens, in terms of mortality and oocyst excretion." (PMID 34794080, 2022). "Effects of BACI, CP1, BP1, and CP+BP in feed s were evaluated at day 21 and 28 on the serum IgY (IgG), IgM, and IgA levels in broiler chickens receiving or not a coccidiosis vaccine." (PMID 34149685, 2021).
colorectal cancer (3 papers, 2014 to 2022). A primary or metastatic malignant neoplasm that affects the colon or rectum. "In this study, we demonstrated that CP is effective also in leukemic cells with a growth inhibitory activity comparable and in some cases even higher than that observed in colorectal cancer cells." (PMID 24980813, 2014). "Moreover, levels of serum copper and ceruloplasmin, which binds approximately 95% of the copper in the plasma, are significantly increased in patients with colorectal cancer compared to healthy controls." (PMID 31083627, 2019).
coronary atherosclerosis (3 papers, 2020 to 2022). Atherosclerosis of the coronary vasculature. "Previously showed that α-1-antitrypsin, 1-acid glycoprotein, ceruloplasmin and CRP are associated with the severity of coronary atherosclerosis." (PMID 36361589, 2022). "In patients with coronary atherosclerosis, a decrease in the level of one isoform and two fragments of ceruloplasmin in the blood serum was identified." (PMID 34948066, 2021).
dengue (3 papers, 2008 to 2020). "Since periodic dengue epidemics occur within the A. polynesiensis range, the competency of CP to transmit dengue and additional pathogens (e.g., chikungunya) would need to be assessed prior to implementing a population replacement program." (PMID 18235849, 2008). "Thus, the CP can potentially play an important role in dengue patient outcomes at early stages of infection." (PMID 19707565, 2009). "On the basis of the evidence obtained so far, especially due to the presence of elevated C4a, we cannot rule out the possibility that CP and/or LP are also involved in determining dengue severity." (PMID 19707565, 2009).
diffuse large B-cell lymphoma (3 papers, 2022 to 2023). "However, one patient with diffuse large B-cell lymphoma (DLBCL) who had a prolonged active COVID-19 infection for 129 days received eight doses of CP until remission." (PMID 36547236, 2022). "However, in tumours of haematopoietic origin—diffuse large B‐cell lymphoma (DLBC) and acute myeloid leukaemia (LAML)—a higher IP‐to‐CP expression was observed, which can be explained by the innate IP expression in haematopoietic cells." (PMID 37097039, 2023).
End Stage Liver Disease (3 papers, 2022 to 2025). Final stage of a liver disease when the liver failure is irreversible and LIVER TRANSPLANTATION is needed. "Serum CP may be low in conditions with marked loss of renal or intestinal protein, in patients with severe end-stage liver disease of any etiology, or in a course of rare neurological diseases." (PMID 37296680, 2023). "By integrating serum sodium levels into the model for end-stage liver disease (MELD) score, the MELD-Na score became a better outcome predictor for HCC patients with worsening liver function compared with the CP and ALBI scores." (PMID 35566676, 2022).
Hydrocephalus (3 papers, 2017 to 2025). Hydrocephalus is an active distension of the ventricular system of the brain resulting from inadequate passage of CSF from its point of production within the cerebral ventricles to its point of absorption into the systemic circulation. "Congenital hydrocephalus can be caused by increased production of CSF by the CP, impaired absorption of CSF in the blood stream, or as in the majority of congenital cases, by obstruction of CSF flow." (PMID 29170629, 2017). "Lack of Dusp16 expression in the CP and the normal morphology of this structure, suggest that CSF overproduction is not the cause of hydrocephalus in Dusp16−/− mutants." (PMID 29170629, 2017). "Moreover, the overall morphology of the CP at E14.5 was normal in Dusp16−/− mutants, thereby suggesting that overproduction of CSF is unlikely to have caused the observed hydrocephalus." (PMID 29170629, 2017).
Hypercholesterolemia (3 papers, 2017 to 2023). An increased concentration of cholesterol in the blood. "Chronic cholestasis, resulting from BDL, led to massive inflammation, hypercholesterolemia, and a drastic decrease in intracellular fatty acid transport; these changes were partially reverted by CP-MSC transplantation." (PMID 29250120, 2017).
hyperferritinemia (3 papers, 2010 to 2025). "This group includes disorders with or without iron overload caused by defects in genes involved in iron metabolism (FTL, SLC40A1, CP), as well as non-iron-related genetic disorders often associated with hyperferritinemia with normal TSAT." (PMID 36768886, 2023). "Inherited isolated hyperferritinemia includes several rare or ultra-rare disorders caused by mutations in genes directly involved in iron metabolism (FTL, CP, SLC40A1) or not, such as GBA1." (PMID 36768886, 2023).
Infertility (3 papers, 2013 to 2021). "Their results demonstrated 10 over-expressed proteins in the infertile group, including: Ubiquitin-conjugating enzyme E2C binding protein (UBE2C), Cystatin-A (CSTA), Dermcidin (DCD), Ceruloplasmin (CP), Ras GTPase-activating-like protein IQGAP1 (IQGAP1)." (PMID 29881623, 2018).
injury (3 papers, 2014 to 2025). Damage inflicted on the body as the direct or indirect result of an external force, with or without disruption of structural continuity. "Our study also highlights the functional significance of GluA3 abundance in the spinal cord in neuropathic pain and synaptic CP-AMPARs caused by nerve injury." (PMID 41129242, 2025). "To determine the functional significance of the GluA3 abundance in neuropathic pain and spinal cord CP-AMPARs induced by nerve injury, we intrathecally injected Gria3-expressing lentiviruses or control lentiviruses in sham and SNL rats 2 weeks after surgery." (PMID 41129242, 2025). "In comparison with mice with sham surgery, a significant inward rectification of the AMPAR mediated I-V curve were observed in ACC pyramidal cells in mice with nerve injury, indicating that the GluA2 containing AMPAR were replaced by CP-AMPAR." (PMID 25359681, 2014). "According to the observed inward rectification of the mean I-V curve in mice with nerve injury, we expect that the potentiated AMPAR mediated responses in the ACC layer V may be sensitive to the inhibition of CP-AMPAR antagonist NASPM." (PMID 24890933, 2014).
Kufor-Rakeb syndrome (3 papers, 2021 to 2024). Kufor-Rakeb syndrome (KRS) is a rare genetic neurodegenerative disorder characterized by juvenile Parkinsonism, pyramidal degeneration (dystonia), supranuclear palsy, and cognitive impairment. "The abnormal brain iron accumulation in the basal ganglia was also observed in other disorders, such as Kufor-Rakeb syndrome (KRS), Aceruloplasminemia (ACEP), Spastic paraplegia 35 (SPG35), and Jaberi-Elahi syndrome (JABELS), which were caused by mutated ATP13A2, CP, FA2H, GTPBP2, respectively." (PMID 38765101, 2024).
metastatic tumors (3 papers, 2017 to 2025). "We found that PTK2 showed differing associations: in metastatic tumors, it correlated positively with MHC, SC and CP, and negatively with EC and AZ, while in primary tumors, it was positively correlated with MHC and SC, but its correlations with AZ were mixed." (PMID 40943183, 2025).
multiple sclerosis (3 papers, 2017 to 2024). A progressive autoimmune disorder affecting the central nervous system resulting in demyelination. "In multiple sclerosis patients, Cu levels in cerebrospinal fluid are increased, possibly by reducing the ferroxidase function of serum ceruloplasmin, due to the oxidative environment in serum." (PMID 35736165, 2022).
oral cancer (3 papers, 2018 to 2024). "Furthermore, serum ceruloplasmin is utilized as a diagnostic biomarker for oral premalignancies and oral cancer." (PMID 34413268, 2021). "Ceruloplasmin serves as a source of Cu(I) ions, which may initiate the process of LDL oxidation and play a role in the malignant transformation of OSF to oral carcinoma." (PMID 30046309, 2018).
osteosarcoma (3 papers, 2006 to 2024). A usually aggressive malignant bone-forming mesenchymal neoplasm, predominantly affecting adolescents and young adults. "Virus bearing the CP FeLV Env variant maintained high titers after concentration allowing for direct visualization of delivery of the luciferase gene in subcutaneous 143B osteosarcoma tumors." (PMID 23767896, 2013). "The functionalized FeS2@CP NPs were introduced to treat osteosarcoma in vitro and in vivo by activating an apoptosis-ferroptosis dual-killing mechanism." (PMID 38561739, 2024). "Through screening retroviral Env libraries, isolates including CP and L1, capable of infecting the human osteosarcoma cell line 143B were identified." (PMID 23767896, 2013). "Although CP Env maintains high titers on 143B cells, its tissue specificity is not limited to osteosarcoma cells." (PMID 23767896, 2013). "Finally, the combination of FeS2@CP NPs-based PTT and CDT strengthened the dual mechanism of cell death and effectively inhibited the growth of osteosarcoma in vitro and in vivo." (PMID 38561739, 2024).
pancreatic ductal adenocarcinoma (3 papers, 2017 to 2021). An infiltrating adenocarcinoma that arises from the epithelial cells of the pancreas. "Ceruloplasmin was suggested as a promising marker for the patients with pancreatic ductal adenocarcinoma because it was highly secreted by PNAC1 cancer stem-like cells, especially those negative for CA19-9." (PMID 28423673, 2017). "To do this, we analyzed serum aspartate aminotransferase (AST) and alanine aminotransferase (ALT) levels collected on patients with pancreatic ductal adenocarcinoma (PDAC) treated on a clinical trial with the fully human agonist CD40 antibody CP-870,893 in combination with gemcitabine chemotherapy." (PMID 34101617, 2021). "Meanwhile, Ceruloplasmin is a promising (prognostic) marker for pancreatic ductal adenocarcinoma (PDAC) in patients negative for CA19-925,26." (PMID 34907282, 2021).
squamous cell carcinoma (3 papers, 2012 to 2021). A carcinoma arising from squamous epithelial cells. "Interestingly, periostin level is significantly higher in squamous cell carcinoma than in adenocarcinoma, and slightly higher in male than in female although not statistically, which is opposite to ceruloplasmin." (PMID 28088789, 2017).
thyroid cancer (3 papers, 2018 to 2021). "In this preliminary study, we show that oxidative stress in thyroid cancer is increased compared to that detected in healthy tissues, as suggested by the statistically higher CP· concentration." (PMID 29371830, 2018). "Given the current data demonstrating the effective growth inhibitory effects of mortalin depletion in non-MTC thyroid cancer cell lines above, we determined whether Mito-CP would also effectively suppress these cells." (PMID 31027376, 2019).
triple-negative breast carcinoma (3 papers, 2021 to 2022). An invasive breast carcinoma which is negative for expression of estrogen receptor (ER), progesterone receptor (PR), and human epidermal growth factor receptor 2 (HER2). "Further, given that the treatment of a triple negative breast cancer phenotype is complicated and challenging, the fact that CP targeted multiple phenotypes of this cell is a very interesting discovery." (PMID 34122605, 2021). "Ceruloplasmin expression was also dramatically downregulated in non-triple-negative breast cancer (TNBC) and non-basal-like BRCA patients compared with that in basal-like and TNBC BRCA patients." (PMID 34413268, 2021).
acute lymphoblastic leukaemia (2 papers, 2014 to 2021). "Of note, the ratio of iP-to-cP expression is significantly higher in pre-B acute lymphoblastic leukemia (ALL) than in acute myeloid leukemia (AML) pediatric patients." (PMID 34206607, 2021). "The higher uptake of CP in leukemic cells could be correlated with the higher cytotoxicity displayed by CP in this type of acute lymphoblastic leukaemia cell lines compared to healthy PBMC, supporting the better selectivity of CP towards cancer cells." (PMID 24980813, 2014).
amyloid diseases (2 papers, 2023 to 2025). "Finally, we identified VUS in genes for which alterations have been reported in the literature in patients with ATTRwt amyloidosis, as it is the case of the CP gene, responsible for ceruloplasmin, and TF gene, coding for transferrin." (PMID 37784196, 2023). "Our findings collectively open new avenues for research into the proteome alterations in amyloid diseases and elucidation of several key proteins that have the potential to be leveraged as biomarkers for V30M ATTRv-PN, including TTR itself, CP, APOE, and the complement pathway proteins such as C3." (PMID 40564999, 2025).
ankylosing spondylitis (2 papers, 2024 to 2025). An autoimmune chronic inflammatory disorder characterized by inflammation in the vertebral joints of the spine and sacroiliac joints. "Previous investigations have substantiated that individual with ankylosing spondylitis manifest significantly elevated levels of serum copper and ceruloplasmin, particularly in severe instances." (PMID 38965390, 2024). "Subsequent research has unveiled heightened levels of serum copper and ceruloplasmin in ankylosing spondylitis patients, correlating with inflammatory activity." (PMID 38965390, 2024).
autoimmune (2 papers, 2015 to 2022). "Therefore, both lack of activation and a too strong activation of the CP can be linked to autoimmunity." (PMID 26074922, 2015). "Serological tests for hepatitis virus, cytomegalovirus, and EB virus, autoimmune antibodies and ceruloplasmin were all negative." (PMID 36561849, 2022).
bleeding disorders (2 papers, 2018 to 2025). "Although bleeding time was prolonged in CP-Tg mice due to the anti-thrombotic properties, it did not cause any bleeding disorders and remained within a safe range." (PMID 29374184, 2018).
brain injury (2 papers, 2021 to 2024). Acute and chronic (see also brain INJURIES, CHRONIC) injuries to the brain, including the cerebral hemispheres, CEREBELLUM, and brain STEM. "The boxplots below show the scores for PCSS, Ocular, CP Screen (Sleep) and PHQ, split by concussion history and biological sex." (PMID 38526765, 2024).